KLK5 (kallikrein related peptidase 5)
Description:
May be involved in desquamation.
Synonyms: KLK-L2; SCTE; KLKL2
Tractability: Small molecule: a structure with a bound ligand is known; a high-quality ligand is known. Antibody: its Gene Ontology location is reachable by antibodies, with high confidence; UniProt places it where antibodies can reach, with medium confidence; UniProt predicts a signal peptide or a membrane-spanning region. PROTAC: a small molecule that binds it is known.
Target class: Serine protease; Enzyme; Serine protease PA clan; Serine protease S1A subfamily; Protease
Gene: Protein-coding gene on chromosome 19 (50,943,299 to 50,953,314, reverse strand). Ensembl gene ENSG00000167754.
Subcellular location: Secreted
Pathways (Reactome):
Developmental Biology: Differentiation of Keratinocytes in Interfollicular Epidermis in Mammalian Skin; Formation of the cornified envelope
Gene Ontology:
Molecular function: peptidase activity; protein binding; serine-type endopeptidase activity; serine-type peptidase activity
Biological process: antibacterial peptide biosynthetic process; positive regulation of G protein-coupled receptor signaling pathway; amelogenesis; cornification; epidermis development; extracellular matrix disassembly; protein maturation; proteolysis
Cellular component: epidermal lamellar body; extracellular region; cytosol; secretory granule
Genetic constraint (gnomAD): Loss-of-function variants: 19 observed, 26.36 expected, observed/expected ratio (o/e) 0.72, 90% interval 0.5 to 1.06. The upper end of that interval is the gene's LOEUF score, 1.06, which puts it in group 4 of 6, group 1 being the genes least tolerant of losing a copy. Missense variants: 374 observed, 395.45 expected, observed/expected ratio (o/e) 0.95, 90% interval 0.87 to 1.03. Synonymous variants: 140 observed, 162.36 expected, observed/expected ratio (o/e) 0.86, 90% interval 0.75 to 0.99.
Homologues: Orthologues: chimpanzee KLK5 (99% identical), macaque KLK5 (94% identical), pig KLK5 (76% identical), rabbit KLK5 (74% identical), rat Klk5 (70% identical), mouse Klk5 (70% identical), tropical clawed frog klk1 (33% identical), Drosophila melanogaster CG32808 (22% identical), Drosophila melanogaster Phae2 (22% identical), Drosophila melanogaster CG3916 (22% identical), Drosophila melanogaster CG4477 (22% identical), Drosophila melanogaster CG12256 (22% identical), and 6 more. Paralogues in human: KLK4 (44% identical), KLK11 (42% identical), KLK14 (41% identical), KLK8 (40% identical), KLK7 (40% identical), KLK12 (37% identical), KLK2 (37% identical), KLK3 (36% identical), KLK1 (33% identical), TMPRSS4 (27% identical), PRSS58 (26% identical), PRSS54 (18% identical).
Diseases named in the same sentence as KLK5 in open-access papers:
KLK5 is named in the same sentence as 88 diseases in open-access papers, as found by Europe PMC text mining. Sharing a sentence is not in itself a finding about the gene and the disease. The quoted sentences say what the papers report.
rosacea (32 papers, 2015 to 2026). A chronic erythematous skin disorder that affects the face. "Kallikrein 5 (KLK5) converts cathelicidin into its active form, LL-37, which has been implicated in inflammation, angiogenesis, and telangiectasis in rosacea." (PMID 39136023, 2024). "Individuals at risk of rosacea express not only abnormally high levels of KLK5 in their epidermis, but also higher levels of LL-37, the proteolytically cleaved cathelicidin, compared with normal individuals." (PMID 35203672, 2022). "The excessive production and activation of kallikerin 5 (KLK5) and cathelicidin have been implicated in the pathogenesis of rosacea." (PMID 33256158, 2020). "The excessive activation of KLK5 causes an exacerbation of dermatoses, such as rosacea and atopic dermatitis." (PMID 29077044, 2017). "The production of KLK5 and cathelicidin and consequent activation of cathelicidin into LL-37 by KLK5 may have a major impact on the development of rosacea-associated erythema and inflammation." (PMID 35203672, 2022). "Therefore, KLK5 inhibitors are considered as therapeutic agents for improving the underlying pathophysiology and clinical manifestation of rosacea." (PMID 35203672, 2022). "Further, activation of epidermal proteases, especially kallikrein (KLK‐5) is also associated with rosacea and may further contribute to the inflammatory process." (PMID 34027084, 2021). "Given that protease activity increases at an alkaline pH, the abnormal epidermal barrier function in rosacea might be associated with enhanced activation of epidermal proteases, especially kallikrein (KLK)-5." (PMID 27649161, 2016). "Therefore, vitamin D likely influences the TLR-2, KLK-5, and LL-37 associated pathway in rosacea and affects the subsequent proinflammatory cascades that can alter the immune system in these patients." (PMID 27649161, 2016). "Therefore, we wondered whether the KLK5–LL-37‒pDC‒IFN-α‒Th17/Th22 axis could play a pathogenic role in driving neoangiogenesis in rosacea." (PMID 36633910, 2023). "However, whether the TLR2/KLK5/cathelicidin pathway in macrophages is involved in the mechanism underlying the efficacy of carvedilol in rosacea remains unknown." (PMID 34322115, 2021). "Patients with rosacea also exhibit abnormally high levels of kallikrein-5 (KLK5), a serine protease that processes CAMP into bioactive fragments such as LL-37, thereby amplifying the inflammatory cascade." (PMID 40149947, 2025). "In line with extensive survey findings, sun exposure demonstrated a significant correlation with rosacea, likely attributed to UV‐induced oxidative stress and the activation of the KLK5‐cathelicidin cascade." (PMID 40741710, 2025). "Elevated levels of various proteases like serine protease kallikrein 5 (KLK5) have been also reported in rosacea." (PMID 38399428, 2024). "The increased abundance of CAMP and KLK5 activity has been shown to increase the levels of bioactive cathelicidin fragments in rosacea patients." (PMID 38450615, 2024). "Taken together, these findings indicate that KLK5 overexpression in rosacea increases cleavage of cathelicidin in the skin." (PMID 36633910, 2023). "KLK5, which is overexpressed in rosacea, mediates processing of cathelicidin into the active LL-37 peptide." (PMID 36633910, 2023). "KLK5 has been shown to be upregulated in patients with rosacea, leading to the aberrant accumulation of active LL37." (PMID 37626650, 2023). "Previous studies have demonstrated that KLK5 and cathelicidin peptides have a functional role in driving an inflammatory response in rosacea." (PMID 36633910, 2023). "Mast cells are one of the major sources of cathelicidins and KLK-5 in the skin and are highly active in rosacea patients." (PMID 38260914, 2023). "KLK-5 enzyme activity is enhanced in the skin of rosacea patients, which also explains the increased levels of LL-37." (PMID 38260914, 2023).
rosacea (continued). "A recent study showed that the expression of dermal serine proteases, KLK5 and cathelicidin, was significantly elevated in rosacea lesions compared with healthy skin." (PMID 35203672, 2022). "Increased KLK5 activity in rosacea generates LL-37 by cleaving cathelicidin, which triggered cutaneous inflammation and erythema." (PMID 35203672, 2022). "In conclusion, we present the first report that carvedilol can alleviate the inflammatory reaction in rosacea via the TLR2/KLK5/cathelicidin pathway in macrophages." (PMID 34322115, 2021). "The TLR2/KLK5 pathway is also important for rosacea, as serine protease KLK5 activity and cathelicidin expression are highly up-regulated in this disease, promoting skin inflammation." (PMID 34322115, 2021). "In vitro, carvedilol decreased TLR2 expression in RAW 264.7 cells, further reducing KLK5 secretion and LL-37 expression and ultimately inhibiting rosacea-like inflammatory reactions." (PMID 34322115, 2021). "Since pro-KLK5 has the ability to activate itself, inhibiting their protease activity is one of the main targets for rosacea treatment." (PMID 33256158, 2020). "Since KLK5 is responsible for the cleavage of inactive cathelicidin into active LL-37, it is implicated, in that elevated levels of LL-37 are the result of high levels of KLK5 in the lesional skin of rosacea." (PMID 33256158, 2020). "Patients with rosacea express upregulated levels of cathelicidin LL-37, a biologically active form of cathelicidin and kallikrein-related peptidase 5 (KLK5), tryptic serine protease expressed in stratum corneum." (PMID 33256158, 2020). "A typical disease is rosacea, in which the skin antimicrobial peptide cathelicidin, cleaved with LL-37 by the activation of excessive KLK5, increases the expression of inflammatory mediators, and causes erythema." (PMID 33256158, 2020). "In mice, TLR-2-induced cathelicidin activation needs functional kallikrein-5 (KLK-5) protease activity for the formation of rosacea-like erythema and angiogenesis." (PMID 30631431, 2018). "Patients with rosacea have elevated levels of cathelicidin and KLK5 protease; an excessive production of LL-37 is suspected to contribute the trigger and the exacerbation of rosacea." (PMID 29077044, 2017). "Additionally, the results highlight that LA can ameliorate rosacea-like dermatitis through dual inhibition of KLK5 and TLR4/NF-κB signaling, while correcting metabolic disturbances, especially in phenylalanine metabolism." (PMID 41668756, 2026). "Additionally, LA inhibited TLR4/nuclear factor (NF)-κB-regulated inflammation by binding to KLK5, thereby improving rosacea." (PMID 41668756, 2026). "Targeting KLK5 activations may help prevent abnormal LL-37 processing and reduce inflammation in rosacea." (PMID 39858288, 2024). "For example, activated TLR2 was reported to elevate rosacea-related kallikrein 5 (KLK5), subsequently producing the pro-inflammatory forms of antimicrobial peptide LL37, and LL37 interacts with TLR2 to activate mTOR signaling, eventually inducing the development of rosacea." (PMID 37780385, 2023). "KLK5, which is overexpressed in rosacea, cleaves cathelicidin into different peptides." (PMID 36633910, 2023). "KLK-5 can also be stimulated by MMP-9 in the skin of rosacea patients." (PMID 38260914, 2023). "Therefore, the inflammation in rosacea can be modulated by inhibiting the generation of LL-37 via inhibition of KLK5 activity, or by directly blocking the release of inflammatory mediators induced by LL-37 in mast cells." (PMID 35203672, 2022). "However, in patients with rosacea, the abnormal activation of cathelicidin into LL-37 due to excessive KLK5 leads to skin inflammation and erythema." (PMID 35203672, 2022).
rosacea (continued). "Cathelicidin is further cleaved into LL-37, its active peptide form, by kallikrein 5 (KLK5), causing leukocyte chemotaxis, activation of NF-kB and promotion of angiogenesis, resulting in morphologic changes in rosacea, such as telangiectasia, facial erythema, papules and pustules." (PMID 35629392, 2022). "Rosacea lesions expressed elevated KLK5 in the basal layer of epidermis along with cathelicidin, in contrast to healthy skin, expressing reduced levels of cathelicidin and KLK5 superficially." (PMID 35203672, 2022). "Excessive levels of KLK5 could result in inflammatory conditions such as atopic dermatitis and rosacea." (PMID 36293365, 2022). "Moreover, TLR2 expression is increased and stimulates KLK5 production by keratinocytes in patients with rosacea." (PMID 34322115, 2021). "Patients with rosacea have an increase in both cathelicidin and kallikrein 5 (KLK5, the serine protease that can cleave cathelicidin precursor protein into the active form), leading to the generation of the pro‐inflammatory forms of antimicrobial peptide (e.g., LL37)." (PMID 33734592, 2021). "Notably, the lesional skin of patients with rosacea was shown to express more KLK-5 than the skin of healthy controls." (PMID 27649161, 2016). "Finally, the results in RAW 264.7 cells confirmed that the TLR2/KLK5/cathelicidin pathway could be enhanced in the rosacea-like inflammation mice model, whereas this was inhibited by pretreatment with carvedilol." (PMID 34322115, 2021). "However, KLK-5 is increased in patients with rosacea and KLK(s)-5 can activate PAR237." (PMID 30631431, 2018). "Abnormal functioning of TLR-2, KLK-5, and cathelicidin or vitamin D response along with epidermal barrier disruption may contribute to the dysregulation of innate immunity and augment the inflammatory cascade in rosacea." (PMID 27649161, 2016). "In rosacea, TLR2 activation increases kallikrein-5 (KLK5) from keratinocytes, generating pro-inflammatory LL-37 fragments that further stimulate mTOR signaling." (PMID 41373451, 2025). "Elevated levels of antimicrobial peptides, KLK5, TLR2, and MMPs have been observed in skin lesional of rosacea patients." (PMID 39692542, 2024). "Increased expression levels of cathelicidin, kallikrein-related peptidase 5 (KLK5), toll-like receptor 2 (TLR-2), and matrix metalloproteinase (MMP) have been observed in patients with rosacea." (PMID 39044833, 2024). "TLR2, KLK5, cathelicidin peptides, and CD68 are all highly expressed in patients with rosacea and rosacea animal models." (PMID 38193038, 2023). "Kallikrein 5 (KLK5) represents the predominant protease responsible for cleaving cathelicidin and shows increased expression in rosacea." (PMID 36633910, 2023). "Rosacea is characterized by immune dysfunction involving both innate and adaptive immunity, with alterations to the TLR2/KLK5/LL37 pathway being the most well-studied pathological mechanism." (PMID 37626650, 2023). "Interestingly, KLK5 and KLK14 were previously shown to activate PAR2 expressed in keratinocytes and intense KLK14 staining was observed in atopic dermatitis and rosacea patients' squamous and granular skin layers." (PMID 40621923, 2025). "Elevated levels of disease characteristic factors, such as KLK5, CAMP, TLR2, and proinflammatory cytokines (such as TNF‐α, IL1β, and IL6), and MMPs have been observed in the skin lesions of human rosacea patients as well as in a mouse model of rosacea induced by LL37." (PMID 39692542, 2024). "In addition, rosacea upregulates the expression level of TLR2, thereby increasing the secretion of KLK5 from keratinocytes." (PMID 39136023, 2024). "Both bacteria showed a similar capacity to induce KLK5 in vitro, indicating that B. oleronius not only provides an essential source for DNA, but also induces cleavage of cathelicidin through upregulation of KLK5 in order to activate pDCs and induce type I IFN production in flare-ups of rosacea." (PMID 36633910, 2023).
rosacea (continued). "Moreover, TLR2, KLK5, cathelicidin peptides, and CD68 were highly expressed in both patients with rosacea and rosacea-like animals." (PMID 34322115, 2021). "The upstream signal or signals of enhanced PAR2, TLR-2, and KLK-5 proteins in rosacea have not been identified yet." (PMID 30631431, 2018). "Because there is no drug to regulate KLK5, our findings pave the way for future studies to investigate the potential use of triterpenoids as an anti-KLK5 drug and as a therapeutic drug against refractory skin diseases such as rosacea and atopic dermatitis." (PMID 29077044, 2017).
breast carcinoma (27 papers, 2002 to 2025). "KLK5 and KLK4 have been associated with poor prognosis in ovarian cancer, and KLK5 has also been shown to be associated with poor prognosis in breast cancer." (PMID 24510347, 2014). "The associations between KLK5 expression and the breast cancer patients' histological grade, tumor size and PR staining were not proven to be statistically significant." (PMID 21906360, 2011). "Extensive statistics were applied in order to investigate the KLK5 expression association with the histological features of breast cancer patients, aiming to examine its clinical value for the discrimination of the cancerous from non-cancerous breast lesions." (PMID 21906360, 2011). "The association of the KLK5 expression levels with the pre-menopausal status of breast cancer patients was expected, due to the drop of circulating estrogens of the post-menopausal women." (PMID 21906360, 2011). "Statistically strong associations were observed between the KLK5 expression and the menopausal status (p = 0.005), as well as the estrogen receptor (ER) staining (p = 0.028) of the breast cancer patients." (PMID 21906360, 2011). "The univariate logistic regression model disclosed a statistically significant (p < 0.001) elevated risk of the patients with reduced KLK5 expression to suffer from breast cancer." (PMID 21906360, 2011). "Statistically significant association of the KLK5 mRNA levels with the ER-negative staining (p = 0.028) and the pre-/peri-menopausal status (p = 0.005) was observed in breast cancer patients." (PMID 21906360, 2011). "Apart from the evaluation of KLK5 expression for the differential diagnosis of breast cancer, we further examined the KLK5 expression status association with breast cancer patients' clinocopathological features, in order to assess its prognostic significance for the patients." (PMID 21906360, 2011). "We next compared KLK5 expression among subgroups of breast cancer patients using the bc‐GenExMiner online tool." (PMID 38090381, 2023). "Online databases, including UALCAN, GEPIA, HPA, Breast Cancer Gene‐Expression Miner, and quantitative PCR and western blot, were used to examine KLK5 messenger RNA and protein expression in breast cancer." (PMID 38090381, 2023). "To further explore the role of KLK5 in breast cancer, we compared the transcriptomes of the KLK5‐high and KLK5‐low groups using TCGA database." (PMID 38090381, 2023). "A total of 1443 co‐expressed genes were significantly correlated with KLK5 in breast cancer (FDR ≤ 0.001, p ≤ 0.001, and |person correlation| ≥ 0.3)." (PMID 38090381, 2023). "KLK5 mRNA levels were significantly downregulated in breast cancer compared with normal tissues in GEPIA, and KLK5 protein expression was consistent with the RNA levels in breast cancer in UALAN." (PMID 38090381, 2023). "KLK5 acts as a tumor suppressor in hormone‐dependent tumors, such as prostate cancer, vaginal cancer, and breast cancer." (PMID 38090381, 2023). "A total of 1246 genes positively correlated with KLK5 expression, and 197 genes negatively correlated with KLK5 in breast cancer." (PMID 38090381, 2023). "Another study showed that enhanced signaling involving the oncogene GNA13 downregulates KLK5 gene transcription, which promotes breast cancer progression." (PMID 38090381, 2023). "Previous studies have consistently indicated that KLK5 is a potential serum biomarker for breast cancer." (PMID 36313631, 2022). "For instance, BAP1 has been demonstrated to stabilize an oncogenic transcription factor KLK5 in breast cancer, promoting breast cancer progression and metastasis." (PMID 35194152, 2022). "The observed cooperative effects of blocking MFGE8 and KLK5/7 with COX-2 inhibition in reducing tumor growth provides an important rationale for developing COX-2 inhibitor-based combination therapies for breast cancer patients." (PMID 33588911, 2021). "Kallikrein-related peptidase 5 (KLK5) protease can inhibit enzymes of mevalonate pathway in breast cancer." (PMID 28373964, 2017).